CD4 (CD4 molecule)
Diseases named in the same sentence as CD4 in open-access papers (continued):
Sharing a sentence is not in itself a finding about the gene and the disease.
infection (continued). "RORγt-expressing CD4+ T cells, which are thought to be Th17-type T cells, were only present in the lungs of mice infected with the reference strains, Mtb H37Ra and H37Rv, at 28, 56 and 112 days post-infection; this type of T cell was not induced in mice infected with Mtb K (lower-left panel)." (PMID 26675186, 2015). "In expressing the force of infection, we did not add a coefficient to translate the fact that individuals with low CD4 cell counts have higher viral loads (thus higher infectiousness) than individuals with high counts; indeed, individuals with low CD4 cell counts might be sexually less active." (PMID 26091253, 2015). "It is likely that mDC and monocyte lineage cells in lymphoid tissue, skin, mucosal surfaces, gastrointestinal tract (GIT) and sites of inflammation could allow seeding of CD4+ T-cell viral reservoirs early following infection or during ART in tissue sites were cART penetration may not be optimal." (PMID 26362311, 2015). "Thus, age-dependent defects in naïve CD4+ T cell trafficking and in the draining lymph node environment result in delayed initiation of antiviral responses and a failure to control WNV, which ultimately contributes to higher rates of mortality after infection." (PMID 26204259, 2015). "However, contrary to what has been reported in other parasite models, we did not detect an increased proportion of FoxP3+ CD4+ T cells in the LI LP at this infection dose, but rather a substantial decrease, a change that was apparent already at day 20 and remained as the infection progressed." (PMID 25942314, 2015). "Thus, although CD4+ T cell-mediated mortality coincides with significantly elevated secretion of IFN-γ, it still remains inconclusive whether IFN-γ is the direct mediator of CD4+ T cell-dependent mortality in these infections." (PMID 26222157, 2015). "Our data also imply that CD4+ or CD8+ T cells—the major source of IL‐2 in most systems—may also play a role in amplifying NK‐cell responses and thus that IL‐2 production by memory T cells may represent an important effector response during re‐infection or after vaccination." (PMID 26420375, 2015). "Finally, as observed in our previous experiments, the lack of HIV-1 activation in unstimulated CD4+ T lymphocytes treated with AZT before infection and co-cultivated with HIV-1 expressing cells indicated that the Gag-specific FACS assay detected de novo produced intracellular Gag molecules only." (PMID 26502902, 2015). "Furthermore, the non-specific CD4+ T lymphocyte-dependent polyclonal hypergammaglobulinaemia that arises as an initial response to FIV infection might also contribute to the lack of effective neutralization observed in this group." (PMID 25395594, 2015). "However, factors related to HIV infection (i.e., duration of infection and CD4 counts) were not analyzed in our study and may influence the HPV type distribution." (PMID 25053972, 2014). "Although our studies did not aim to establish whether the infection of CD4+ and CD8+ with CVB3 is productive, the fact that the level of VP1 protein following CVB3 infection decreases with time suggests that the infection is transiently productive and can be cleared." (PMID 24816846, 2014). "Infection with C. parvum in immunocompetent persons often results in asymptomatic or mild self-limited disease, but in HIV-infected patients, particularly those with low CD4 counts, infection may result in chronic or life-threatening diarrhea, or extraintestinal disease." (PMID 24523958, 2014). "Thus our results add a new possibility as CD4+ cells from chronically infected patients may express HCV-core, either due to infection or uptake of the viral protein shown to be present in the serum and CD4+ T cells expressing HCV-core can be transformed into Treg cells." (PMID 24465502, 2014).
infection (continued). "Some CD4 epitopes identified in human vaccinees were not seen in the naturally infected individuals; it might be expected that some epitopes present in the context of vaccination would be lost on infection." (PMID 24788397, 2014). "Unfortunately, we did not have information on the date of infection for most of the patients, although higher CD4 counts, lower percentage of patients in CDC C stage and a slightly higher percentage of recent infections in the latter calendar years could indicate an earlier HIV diagnosis." (PMID 24637804, 2014). "However, using similar blood-derived, myeloid DC models, others found that DC did not support HIV-1 cis infection yet could result in high levels of trans infection of CD4+ T cells." (PMID 24278768, 2013). "Thus, four main hypothesis can be raised: 1) Individuals that lost circulating IFN-gamma CD4+ T cells have cleared infection and have not been re-infected." (PMID 24206576, 2013). "Interestingly, we found markedly improved T cell responses and clearance of normally chronic LCMV Clone 13 infection when either myeloid cells or T cells lacked IL-10 production and mice depleted of monocytes/macrophages or CD4+ T cells exhibited reduced overall levels of IL-10 mRNA." (PMID 24244162, 2013). "Naïve CD4+ T-cells could only be isolated from peripheral blood from two of the five patients (patients 2 and 5) and those cells from patient 2 did not contain any detectable HIV-1 DNA (0 copies per 10000 naïve T-cells analyzed) indicating an infection frequency of >10000 cells/HIV-1 DNA molecule." (PMID 23818847, 2013). "Taken together, non-Treg CD4+ T cells from liver on day 7 of infection might be under the control of two different pathways: one that is iNOS/IL-10-dependent, to control resident and activated CD4+ T cells, and a second that is Treg-dependent, to control the newcomer CD4+ T cells." (PMID 24312297, 2013). "Furthermore, non-productive infection of HHV-6B in DC could be transmitted to allogenic primary CD4+ T cells upon co-culture and converted to productive replication." (PMID 23526966, 2013). "However, protection from chronic T. muris infection observed in Itgb8 (CD11c-Cre) mice did not correlate with enhanced type 2 cytokine production from any cell types apart from CD4+ T-cells (data not shown), and protection from infection was completely dependent on CD4+ T-cells." (PMID 24098124, 2013). "However, we could not detect CD4+ T-cellsin this assay, which was most likely owing to decreased expression of the CD4+ receptor following T-cell activation and subsequent infection." (PMID 23658782, 2013). "Furthermore, although integrated proviral infection is found in both memory and naïve resting CD4+ T cells without the need of cell activation, integration in naïve cells was lower than that in memory cells, suggesting that restriction of infection occurs at the first steps of virus life cycle." (PMID 24244453, 2013). "Thus, an alternative explanation for the expulsion of a normally chronic infection of T. muris by Itgb8 (CD11c-Cre) mice is that, in the absence of early CD4+ T-cell TGFβ signalling, mice produce a Th2-type response instead of the usual non-protective Th1 response." (PMID 24098124, 2013). "While Bim has been found to have a role in mediating activated T cell contraction after antigen clearance following infection with certain pathogens, the signals that lead to Bim-mediated apoptosis in most CD4+ T cells but not those fated to enter the memory pool remain unknown." (PMID 23840678, 2013). "A spontaneous HIV production was even detectable in vitro in all memory CD4 T cell subsets over the 13 day-long culture, re-emphasizing the hypothesis this reservoir might not represent a latent reservoir yet at this early stage of infection." (PMID 23691172, 2013).
infection (continued). "However, given that these animals still mount a strong infection-driven CD4 T cell response (results not shown) another possibility could be a difference in ESAT-6 availability during the two conditions." (PMID 24349004, 2013). "Indeed, DC-SIGN dependent recognition of HIV gp120 might concentrate HIV-1 particles on the DC surface such that the probability of virus interaction with CD4 and CCR5 and productive infection in cis is enhanced, though the potential benefit to HIV-1 replication is questionable." (PMID 23593001, 2013). "Thus, HS may compensate for low level CD4 expression and induce a sufficiently high viral particle concentration for infection that CD4 by itself would not achieve." (PMID 24312095, 2013). "Also, a decrease in the fractions of APO2.7-positive HIV-1-infected CD4+ T cells was observed in tissues infected with HIV-1BaL from 13.0±1.3% to 8.8±1.3% and from 5.7±1.0% to 4.1±1.1% of CD8− p24gag+ T cells on day 6 and 9 post infection, respectively (n = 6, p<0.05)." (PMID 23408885, 2013). "Also, information on HIV-related variables such as nadir CD4 counts, history of prior immunosuppression and time since infection was not available and could therefore not be controlled for in the analyses." (PMID 23472184, 2013). "However, percentages of CD4+ T cells were not statistically significant at any single experimental time point, and the two animals that better control viral load were those with higher percentages of CD4+ T cells post-infection." (PMID 23853592, 2013). "The initial testing using bulk PBMC (wherein all functions are registered in the ID50) may be followed by testing of potent samples in parallel using NK-depleted PBMC or purified CD4+ T cells, with or without antibodies washed out after infection (ie. with or without NK or FcR effects present)." (PMID 22509241, 2012). "However, infection was controlled thereafter and it did not result in CD4+T-cell depletion." (PMID 23336082, 2012). "Furthermore, infection of T cell-specific conditional FOXO3-deficient mice with LCMV, fully recapitulated the enhanced CD8 T cell expansion seen in global FOXO3−/− mice; even in the absence of CD4 T cells." (PMID 22359505, 2012). "An observation that was consistent in DR1 and B10 mice after NC infection was that the pattern of secretion of IL-2, IFN-γ, and IL-4 was independent of epitope specificity or whether epitopes were major or minor in terms of the number of stimulated CD4 T cells." (PMID 22457834, 2012). "Interestingly, we detected a rapid downregulation of both CD8+ and CD4+CD8+ T cells, suggesting one mechanism of the PRRSV-mediated delay in initiation of virus-specific adaptive immunity is by altering the function and frequency of important lymphocytes early post-infection." (PMID 22340040, 2012). "As all three had a CD4+ T cell count >400 post-SI, it is unlikely that lower breadth and potency simply reflected a lack of T cell help that could arise at terminal stages of infection." (PMID 22479183, 2012). "However, in mice, depletion of CD4+ cells has no observed effect on course or outcome of infection." (PMID 21912565, 2012). "Next, to investigate the potential for infection-induced qualitative shifts in maternal Treg suppressive potency, Foxp3GFP reporter mice on the C57Bl/6 background were substituted for mating with Balb/c males so that maternal Foxp3+ Tregs could be purified as GFP+ CD4 cells by FACS directly ex vivo." (PMID 22916020, 2012). "The VRC vaccine regimen also induces: durable, concurrent, polyfunctional CD4+ and CD8+ T-cell responses specific for multiple HIV antigens; and central memory and effector CD8+ T cell responses with antiviral activity, which may play a role in preventing infection and controlling chronic infection." (PMID 21857901, 2011).
infection (continued). "Finally, our results support the notion that the cytokines selected to profile CD4+ T cell specific responses upon infection or vaccination should not rely only in IFN-γ secreting cells, but on the assessing of multi-cytokines at different time-points and by using different readout technologies." (PMID 21931646, 2011). "Additionally, auxiliary information on markers of advanced infection that could potentially impact the FRR to a large degree, including duration of HIV infection, CD4 cell counts, and age should also be collected to determine whether FRR varies significantly by these factors." (PMID 21408182, 2011). "Both the absolute CD4+ T cell counts and percentages were significantly higher in female than male population, indicating the true difference in the CD4+ T cell values and not the influence of total lymphocyte counts that might vary with the other infection load in the population." (PMID 21967708, 2011). "Because the great majority of α4β7+ CD4+ T cells in the genital mucosa express high levels of CCR5 it is reasonable to envision that, in the contest of a STD-induced immune response, DC-T cell interactions in the genital mucosa may promote infection of CD4+ T-cells by R5 viruses." (PMID 21284901, 2011). "In infections of quiescent CD4+ T-cells, reverse transcription can occur, but is often not completed and displays greatly reduced kinetics, or PICs might not be imported into the nucleus efficiently when levels of ATP are lacking; therefore integration can be delayed or may not occur at all." (PMID 21722380, 2011). "Similarly, for vaccine strategies that aim toreduce the availability of target CD4+CCR5+ cells atsites of transmission, our study suggests that CCR5 expression must be loweredto a level that restricts the formation of gp120-CCR5 complexes to below in order to prevent infection of target cells." (PMID 21647388, 2011). "To conclude in this study utilising tissue specific IL-4Rα−/− mice we demonstrate that upon infection with L. mexicana initial lesion growth is dependent on a non-CD4+ T cell population responsive to IL-4/IL-13, while progressive infection is dependent on CD4+ T cells responsive to IL-4." (PMID 21245915, 2011). "Thus, it is possible that the selection factor for better CD4 usage we observed in the RP macaques following acute R5 SHIVSF162P3N infection could be due to initially low CCR5 and not CD4 expressions on T lymphocytes." (PMID 21760891, 2011). "Further, more recent evidence suggests CD69 may directly influence the development of Treg CD4+ T cells, enhance differentiation of Th17 cells, and regulate TGF-beta secretion, and thus may play a major role in regulating immune responses to infections such as SIV/HIV." (PMID 22096538, 2011). "In contrast, most HIV-1 Env proteins derived from the blood of these subjects were not able to mediate infection of cells with low CD4 surface expression and could only infect cells with high CD4 levels, indicating adaptation for replication in activated T cells in the peripheral blood." (PMID 22007152, 2011). "The iATP level detected after mitogen stimulation, as performed in our assay, may represent the maximum excitability of the CD4+ effector cells; although not antigen-specific, the observed iATP level may resemble an activation level analogous to that occurring during an acute infection." (PMID 21533133, 2011). "Interestingly, while Th1 responses in Irf5-/- mice were severely impaired 4 weeks after infection, expression of IRF-5 was not required during the first 2 weeks of infection, since the frequency of IFNγ-producing CD4+ T-cells in Irf5-/- mice was comparable to WT mice." (PMID 21253574, 2011). "At the acute stage of infection, not only was the high viral load detected in the intestinal mucosa, but SIV infection resulted in pathogenic effects as indicated by the depletion of a significant proportion of CD4+ T cells in the guts but not in peripheral blood." (PMID 21994611, 2010).
infection (continued). "Thus, the factors regulating CD4+ T cell subset targeting in vivo may be central to defining the outcome of infection in natural or non-natural hosts." (PMID 20865163, 2010). "In addition, gp120/CD4 interactions may promote the activation, expansion and suppressive potential of Treg v effector cells, by up-regulating expression of the anti-apoptotic factor BCL-2, thereby prolonging cell survival and infection." (PMID 20174666, 2010). "However, these responses in the absence of raltegravir could hardly control infection, as shown by the analysis of the CD4 counts of one of our study groups prior to treatment start." (PMID 20233398, 2010). "Myeloid dendritic cells were first implicated in HIV-1 pathogenesis nearly two decades ago when it was found that HIV-1 exposed DCs could greatly stimulate infection without first becoming infected and that purified DCs could nucleate clusters of CD4+ T cells and drive their infection in vitro." (PMID 21994702, 2010). "Regulatory T cells might suppress strong virus-specific CD8+ T cell responses, but this appears unlikely because there is no significant change in CD4+CD25+FoxP3+ T cell frequency following infection, and primary LCMV-specific CD8+ T cells response were unabated in CVB3-infected animals." (PMID 19834548, 2009). "However the disease-to-infection ratio was elevated for HIV seropositive participants irrespective of CD4 count whether using the restrictive definition or the more open definition of pathogen." (PMID 19159487, 2009). "Furthermore, CD4+ T cells (and potentially B cells) may be the major source of IL-10 during infection since plasma IL-10 does not increase above baseline levels in RAG−/− mice except on day 3 pi of PyL infection." (PMID 18401464, 2008). "Similarly, CD4+ T-cell counts in the group of triple infection (ranged from 245 to 577 cells/ul with a mean of 404 cells/ μl) also tended to be higher than that in HIV mono-infection though statistical significance was not reached." (PMID 19098990, 2008). "However, CD4-positive T cells from these EUs appear more sensitive to the HIV-1 inhibitory effect of β-chemokines, suggesting the existence of yet unknown mechanisms influencing the role of CCR5 in infection." (PMID 17651505, 2007). "Although the reduction we observe in DC-SIGN mediated transfer of HIV-1 to CD4+ lymphocytes is low any reduction in DC-SIGN mediated capture of virus at sites of exposure may have a significant repercussion on lowering rates of transmission, given the relative inefficiency of infection." (PMID 17263871, 2007). "The inhibition of multiple infections by CD4 down-modulation, however, may not be negligible." (PMID 17967052, 2007). "However, in our study we do not observe inhibition of infection of CD4+ T-lymphocytes." (PMID 17263871, 2007). "However, it is possible that the absence of CD4 might reduce the amount of syncytia and therefore it was important to analyse infection by additional techniques." (PMID 17645788, 2007). "Integrated analyses indicate increased MHC I–mediated signaling (e.g., a non-canonical CD4+ TEM axis) and a rebalancing of infection-related programs." (PMID 41394852, 2025). "In scenarios where IFN-γ is overexpressed, such as upon transfer of antigen-specific CD4+ T cells, blocking IFN-γ results in increased TFH cell frequencies regardless of the infection route." (PMID 40169810, 2025). "This is evident by the addition of CD4 mAb RPA-T4, which completely blocks infection of cocultured non-infected CD4+ T cells while further enhancing infection." (PMID 40130873, 2025). "Even though the role of CD4+ T cells has not been extensively studied in oral HSV-1 infection models, their presence was noted in the TG of HSV-1-infected mice at 15 days post-infection using the lip scarification model." (PMID 40431612, 2025).